OPA1 (OPA1 mitochondrial dynamin like GTPase)
Description:
Dynamin-related GTPase that is essential for normal mitochondrial morphology by mediating fusion of the mitochondrial inner membranes, regulating cristae morphology and maintaining respiratory chain function. Exists in two forms: the transmembrane, long form (Dynamin-like GTPase OPA1, long form; L-OPA1), which is tethered to the inner mitochondrial membrane, and the short soluble form (Dynamin-like GTPase OPA1, short form; S-OPA1), which results from proteolytic cleavage and localizes in the intermembrane space. Both forms (L-OPA1 and S-OPA1) cooperate to catalyze the fusion of the mitochondrial inner membrane. The equilibrium between L-OPA1 and S-OPA1 is essential: excess levels of S-OPA1, produced by cleavage by OMA1 following loss of mitochondrial membrane potential, lead to an impaired equilibrium between L-OPA1 and S-OPA1, inhibiting mitochondrial fusion. The balance between L-OPA1 and S-OPA1 also influences cristae shape and morphology (By similarity). Involved in remodeling cristae and the release of cytochrome c during apoptosis (By similarity). Proteolytic processing by PARL in response to intrinsic apoptotic signals may lead to disassembly of OPA1 oligomers and release of the caspase activator cytochrome C (CYCS) into the mitochondrial intermembrane space (By similarity). Acts as a regulator of T-helper Th17 cells, which are characterized by cells with fused mitochondria with tight cristae, by mediating mitochondrial membrane remodeling: OPA1 is required for interleukin-17 (IL-17) production (By similarity). Its role in mitochondrial morphology is required for mitochondrial genome maintenance. [Dynamin-like GTPase OPA1, long form]: Constitutes the transmembrane long form (L-OPA1) that plays a central role in mitochondrial inner membrane fusion and cristae morphology. L-OPA1 and the soluble short form (S-OPA1) form higher-order helical assemblies that coordinate the fusion of mitochondrial inner membranes. Inner membrane-anchored L-OPA1 molecules initiate membrane remodeling by recruiting soluble S-OPA1 to rapidly polymerize into a flexible cylindrical scaffold encaging the mitochondrial inner membrane. Once at the membrane surface, the formation of S-OPA1 helices induce bilayer curvature. OPA1 dimerization through the paddle region, which inserts into cardiolipin-containing membrane, promotes GTP hydrolysis and the helical assembly of a flexible OPA1 lattice on the membrane, which drives membrane curvature and mitochondrial fusion. Plays a role in the maintenance and remodeling of mitochondrial cristae, some invaginations of the mitochondrial inner membrane that provide an increase in the surface area. Probably acts by forming helical filaments at the inside of inner membrane tubes with the shape and dimensions of crista junctions (By similarity). The equilibrium between L-OPA1 and S-OPA1 influences cristae shape and morphology: increased L-OPA1 levels promote cristae stacking and elongated mitochondria, while increased S-OPA1 levels correlated with irregular cristae packing and round mitochondria shape (By similarity). [Dynamin-like GTPase OPA1, short form]: Constitutes the soluble short form (S-OPA1) generated by cleavage by OMA1, which plays a central role in mitochondrial inner membrane fusion and cristae morphology. The transmembrane long form (L-OPA1) and the S-OPA1 form higher-order helical assemblies that coordinate the fusion of mitochondrial inner membranes. Inner membrane-anchored L-OPA1 molecules initiate membrane remodeling by recruiting soluble S-OPA1 to rapidly polymerize into a flexible cylindrical scaffold encaging the mitochondrial inner membrane. Once at the membrane surface, the formation of S-OPA1 helices induce bilayer curvature. OPA1 dimerization through the paddle region, which inserts into cardiolipin-containing membrane, promotes GTP hydrolysis and the helical assembly of a flexible OPA1 lattice on the membrane, which drives membrane curvature and mitochondrial fusion. Excess levels of S-OPA1 produced by cleavage by OMA1 following stress conditions that induce loss of mitochondrial membrane potential, lead to an impaired equilibrium between L-OPA1 and S-OPA1, thereby inhibiting mitochondrial fusion. Involved in mitochondrial safeguard in response to transient mitochondrial membrane depolarization by mediating flickering: cleavage by OMA1 leads to excess production of S-OPA1, preventing mitochondrial hyperfusion (By similarity). Plays a role in the maintenance and remodeling of mitochondrial cristae, some invaginations of the mitochondrial inner membrane that provide an increase in the surface area. Probably acts by forming helical filaments at the inside of inner membrane tubes with the shape and dimensions of crista junctions (By similarity). The equilibrium between L-OPA1 and S-OPA1 influences cristae shape and morphology: increased L-OPA1 levels promote cristae stacking and elongated mitochondria, while increased S-OPA1 levels correlated with irregular cristae packing and round mitochondria shape (By similarity). [Isoform 1]: Coexpression of isoform 1 with shorter alternative products is required for optimal activity in promoting mitochondrial fusion. [Isoform 4]: Isoforms that contain the alternative exon 4b are required for mitochondrial genome maintenance, possibly by anchoring the mitochondrial nucleoids to the inner mitochondrial membrane. [Isoform 5]: Isoforms that contain the alternative exon 4b are required for mitochondrial genome maintenance, possibly by anchoring the mitochondrial nucleoids to the inner mitochondrial membrane.
Synonyms: KIAA0567; NTG; FLJ12460; NPG; MGM1; BERHS; MTDPS14; MTDPS14A; MTDPS14B; largeG
Tractability: Small molecule: a structure with a bound ligand is known. Antibody: UniProt predicts a signal peptide or a membrane-spanning region. PROTAC: ubiquitination databases record sites on it; its protein half-life has been measured; a small molecule that binds it is known.
Target class: Enzyme; Hydrolase
Gene: Protein-coding gene on chromosome 3 (193,593,144 to 193,697,811, forward strand). Ensembl gene ENSG00000198836.
Subcellular location: Mitochondrion inner membrane (Dynamin-like GTPase OPA1, long form); Mitochondrion intermembrane space (Dynamin-like GTPase OPA1, short form)
Subcellular location (Human Protein Atlas): Mitochondria; Nucleoplasm
Pathways (Reactome):
Metabolism of proteins: Mitochondrial protein degradation
Programmed Cell Death: Regulation of Apoptosis
Gene Ontology:
Molecular function: cardiolipin binding; GTPase activity; GTPase-dependent fusogenic activity; membrane bending activity; phosphatidic acid binding; protein binding; magnesium ion binding; microtubule binding; GTP binding
Biological process: cellular senescence; cristae formation; GTP metabolic process; inner mitochondrial membrane organization; membrane tubulation; mitochondrial fusion; mitochondrial inner membrane fusion; mitochondrion organization; negative regulation of apoptotic process; negative regulation of endoplasmic reticulum stress-induced intrinsic apoptotic signaling pathway; negative regulation of release of cytochrome c from mitochondria; protein complex oligomerization; visual perception; axonal transport of mitochondrion; mitochondrial fission; peroxisome fission; positive regulation of interleukin-17 production; positive regulation of T-helper 17 cell lineage commitment; membrane fusion; negative regulation of intrinsic apoptotic signaling pathway; regulation of mitochondrion organization
Cellular component: membrane; mitochondrial crista; mitochondrial inner membrane; mitochondrial intermembrane space; mitochondrial outer membrane; mitochondrion; dendrite; mitochondrial membrane; axon cytoplasm
Genetic constraint (gnomAD): Loss-of-function variants: 34 observed, 89.95 expected, observed/expected ratio (o/e) 0.38, 90% interval 0.29 to 0.5. The upper end of that interval is the gene's LOEUF score, 0.5, which puts it in group 2 of 6, group 1 being the genes least tolerant of losing a copy. Missense variants: 668 observed, 888.47 expected, observed/expected ratio (o/e) 0.75, 90% interval 0.7 to 0.8. Synonymous variants: 272 observed, 288.39 expected, observed/expected ratio (o/e) 0.94, 90% interval 0.85 to 1.04.
Gene-disease validity (ClinGen):
ClinGen rates the evidence that OPA1 causes each of these diseases.
OPA1-related optic atrophy with or without extraocular features (semidominant): Definitive. Any primary mitochondrial disease in which the cause of the disease is monoallelic or biallelic variants in the OPA1 gene.
Leigh syndrome (autosomal recessive): Moderate. A progressive neurological disease defined by specific neuropathological features associating brainstem and basal ganglia lesions.
Homologues: Orthologues: chimpanzee OPA1 (99% identical), pig OPA1 (97% identical), rat Opa1 (96% identical), rabbit OPA1 (95% identical), macaque OPA1 (93% identical), mouse Opa1 (91% identical), guinea pig OPA1 (89% identical), tropical clawed frog opa1 (82% identical), zebrafish opa1 (75% identical), Drosophila melanogaster Opa1 (50% identical), Caenorhabditis elegans eat-3 (48% identical). Paralogues in human: DNM1 (16% identical), DNM2 (15% identical), MX2 (15% identical), DNM3 (15% identical), DNM1L (14% identical), MX1 (14% identical).
Diseases named in the same sentence as OPA1 in open-access papers:
OPA1 is named in the same sentence as 319 diseases in open-access papers, as found by Europe PMC text mining. Sharing a sentence is not in itself a finding about the gene and the disease. The quoted sentences say what the papers report.
autosomal dominant optic atrophy (221 papers, 2008 to 2026). An autosomal dominant hereditary condition characterized by optic atrophy and progressive visual loss. "Autosomal dominant optic atrophy (ADOA) is an inherited optic neuropathy primarily caused by mutations in OPA1." (PMID 41984835, 2026). "Mitochondrial fusion proteins can regulate apoptosis by inhibiting cytochrome C, and autosomal dominant optical atrophy (ADOA) is caused by opa1 mutations." (PMID 40438494, 2025). "Variants in the OPA1 gene are associated with autosomal dominant optic atrophy, but some OPA1 mutations have additional clinical features, including hearing loss, ataxia, and peripheral neuropathy." (PMID 40426046, 2025). "A clear example of this was the demonstration of successful restoration of mitochondrial function when the OPA1 protein deficiency was eliminated in Autosomal Dominant Optic Atrophy." (PMID 41369368, 2025). "Genetic disorders with imbalances of elongation/fragmentation are known to impact in vivo SKM oxidative capacity, such as in dominant optic atrophy due to mutations of the pro‐fusion gene Opa1." (PMID 40343403, 2025). "–46 The two most common mitochondrial optic neuropathies are autosomal dominant optic atrophy associated with pathogenic variants in OPA1 and LHON with three mtDNA variants (m.3460G>A, m.11778G>A and m.14484T>C) accounting for ∼90% of cases." (PMID 40465263, 2025). "Heterozygous variants in OPA1 are a common cause of autosomal dominant optic atrophy as well as Behr syndrome, high myopia, vitreoretinal detachment, and congenital cataracts." (PMID 40428427, 2025). "For a variant in MFSD8 linked to neuronal ceroid lipofuscinosis and non‐syndromic retinopathy, as well as variants in OPA1‐associated with dominant optic atrophy, we found strong concordance between minigene assay results and patient‐derived cDNA analyses." (PMID 40304364, 2025). "Mutations in OPA1 cause autosomal dominant optic atrophy (DOA), a neurodegenerative disorder primarily affecting the optic nerve." (PMID 41000071, 2025). "OPA1 mutations in humans can lead to neurodegenerative disease, specifically dominant optic atrophy (DOA)." (PMID 40722980, 2025). "Within this deletion, the haploinsufficiency of OPA1, associated with autosomal dominant optic atrophy, is likely responsible for the ophthalmological anomalies." (PMID 38641846, 2024). "Autosomal dominant optic atrophy (ADOA) is an inherited optic neuropathy most frequently associated with OPA1 mutations." (PMID 39264859, 2024). "Through phenotyping of macaques carrying a pathogenic OPA1:p.A8S variant, we identify a genetic model of autosomal dominant optic atrophy." (PMID 38969634, 2024). "Variants in the OPA1 gene will disrupt mitochondrial functions, causing a mitochondrial disease known as Autosomal Dominant Optic Atrophy (ADOA)." (PMID 38641846, 2024). "Mutations in Opa1, Opa3, and Opa7, which are crucial genes for regulating mitochondrial dynamics, have been suggested to be associated with autosomal dominant optic atrophy." (PMID 37762596, 2023). "It was initially found that OPA1 is associated with autosomal dominant optic atrophy, and the OPA1 gene is the most common mutation site of optic atrophy." (PMID 37603376, 2023). "Dominant optic atrophy (DOA) is a rare disease mainly caused by mutations in the gene coding the mitochondrial protein optic atrophy type 1 (OPA1)." (PMID 37863658, 2023). "In this context, mutations in the OPA1 gene, which codes for a mitochondrial protein that controls mitochondrial fusion, have been linked to dominant optic atrophy (DOA)." (PMID 37736113, 2023). "Pathogenic mutations in the Opa1 gene are linked to the non-syndromic autosomal dominant optic atrophy (ADOA) and other syndromes bearing important neurological defects." (PMID 36307526, 2023).
autosomal dominant optic atrophy (continued). "Mitochondrial dysfunction and mitophagy are often hallmarks of neurodegenerative diseases such as autosomal dominant optic atrophy (ADOA) caused by mutations in the key mitochondrial dynamics protein optic atrophy 1 (Opa1)." (PMID 34389813, 2022). "OPA1 mutations are the most frequent cause of autosomal dominant optic atrophy (ADOA), characterized by an indolent, slowly progressive, bilateral, symmetric loss of retinal ganglion cells, leading to moderate visual loss." (PMID 36348444, 2022). "In 2000, OPA1 mutations, primarily frameshift and missense variants, were first identified as the cause of dominant optic atrophy (DOA), a blinding disease characterized by retinal ganglion cell degeneration leading to optic neuropathy." (PMID 36157077, 2022). "Mutation of OPA1 gene has long been associated with dominant optic atrophy, but neurodegenerative symptoms had also been reported, as such parkinsonism and dementia, multiple sclerosis-like disorder, and fatal infantile mitochondrial encephalomyopathy." (PMID 35509884, 2022). "Optic atrophy 1 (Opa1) is a nuclear-encoded mitochondrial protein causing autosomal dominant optic atrophy, and it is a key player in mitochondrial fusion and cristae morphology regulation." (PMID 35682755, 2022). "Certain neuropathies, for example, are caused by mutations in Opa1 (autosomal dominant optic atrophy, ADOA) and Mfn2 (Charcot-Marie-Tooth disease type 2A, CMT2A), where patient cells have clear mitochondrial morphology imbalance and dysfunction." (PMID 34698563, 2022). "Ataxia can be the first symptom in rare patients with autosomal dominant optic atrophy (ADOA) due to OPA1 gene mutations." (PMID 33802970, 2021). "Mild or subclinical dominant optic atrophy due to hypomorphic alleles that alter splicing has been associated with OPA1 (optic atrophy 1)." (PMID 34209753, 2021). "Our study adds a significant number of novel variants to the mutation spectrum of the OPA1 gene and will thereby facilitate genetic diagnostics of patients with suspected dominant optic atrophy." (PMID 34242285, 2021). "OPA1 deficient mice (Opa1+/−), a model of autosomal dominant optic atrophy, which is also characterized by selective RGC death, display RGC dendritic atrophy and accumulation of fragmented mitochondria at dendrites prior to overt visual deficits and RGC loss." (PMID 33916246, 2021). "Mutations in OPA1, which encodes for a dynamin‐like GTPase protein, cause autosomal dominant optic atrophy (DOA)." (PMID 34014035, 2021). "Among these were SIRT3 associations with proteins involved in mitochondrial organization, including OPA1, a dynamin-related guanosine triphosphatase mutated in dominant optic atrophy." (PMID 33857259, 2021). "OPA1 mutations account for 60% of dominant optic atrophy (DOA) cases, and the prevalence of the disease has recently been revised to 1 in 34,000." (PMID 32858900, 2020). "Very interesting, it is reported that mutations in OPA1 gene, resulting in autosomal dominant optic atrophy (ADOA), are associated with multiple sclerosis-like disorder in patients." (PMID 32290388, 2020). "Variants in the OPA1 gene are mostly related with autosomal dominant optic atrophy (DOA) (OMIM#165500)." (PMID 32883255, 2020). "The structure of one of these proteins is known, OPA1, named for the neurological disease caused by its mutation, dominant optic atrophy." (PMID 32581834, 2020). "For example, Mfn2 deficiency causes Charcot–Marie–Tooth (CMT) disease type 2A in 20–40% of CMT cases, while OPA1 mutations cause dominant optic atrophy (DOA)." (PMID 31947766, 2020). "Defects in either, or both processes, have been associated to dominant optic atrophy, which is characterized by OPA1 mutations in humans." (PMID 32455165, 2020). "Mutations in genes of fusion essential proteins, OPA1 and Mfn2, have been associated with two neurodegenerative diseases, autosomal dominant optic atrophy (ADOA) and CMT type 2A, respectively." (PMID 32455165, 2020).